CSPG4P13 (chondroitin sulfate proteoglycan 4 pseudogene 13)
Gene: Transcribed unprocessed pseudogene on chromosome 15 (77,894,684 to 77,904,674, forward strand). Ensembl gene ENSG00000260139.
Diseases named in the same sentence as CSPG4P13 in open-access papers:
CSPG4P13 is named in the same sentence as 1 disease in open-access papers, as found by Europe PMC text mining. Sharing a sentence is not in itself a finding about the gene and the disease.
CSPG4P13 shares sentences with these, for which no sentence is quoted: emphysema (1 paper).